PRR23D1 (proline rich 23 domain containing 1)
Tractability: No criterion of Open Targets' tractability assessment is met for any kind of drug.
Gene: Protein-coding gene on chromosome 8 (7,539,627 to 7,542,450, forward strand). Ensembl gene ENSG00000255251.
Gene Ontology:
Molecular function: protein binding
Genetic constraint (gnomAD): Loss-of-function variants: 0 observed, 0.55 expected, observed/expected ratio (o/e) 0, 90% interval 0 to 1.83. That is too few expected variants to judge how well the gene tolerates losing a copy. Missense variants: 0 observed, 4.5 expected, observed/expected ratio (o/e) 0, 90% interval 0 to 0.67. Synonymous variants: 0 observed, 2.02 expected, observed/expected ratio (o/e) 0, 90% interval 0 to 1.34.
Homologues: Paralogues in human: PRR23D2 (100% identical), PRR23C (25% identical), PRR23B (25% identical), PRR23A (25% identical), PRR23E (12% identical).